AQP3 (aquaporin 3 (Gill blood group))
Diseases named in the same sentence as AQP3 in open-access papers (continued):
Sharing a sentence is not in itself a finding about the gene and the disease.
pancreatic ductal adenocarcinoma (5 papers, 2020 to 2025). An infiltrating adenocarcinoma that arises from the epithelial cells of the pancreas. "In pancreatic ductal adenocarcinoma cells BxPC3, AQP3 and AQP5 facilitate H2O2 influx, and silencing these homologs results in impaired cell migration." (PMID 39125952, 2024). "Studies have shown that AQP3 is overexpressed in LC, CRC, oral squamous cell carcinomas and pancreatic ductal adenocarcinoma." (PMID 39346734, 2024). "AQP3 and AQP5 are overexpressed in pancreatic ductal adenocarcinoma, playing key roles in cell migration, proliferation, and invasion." (PMID 35455986, 2022). "Interestingly, AQP3 and AQP5 expression patterns vary during the progression of pancreatic ductal adenocarcinoma." (PMID 39941100, 2025). "Interestingly, AQP3-, AQP5- and double-silenced human pancreatic ductal adenocarcinoma cells exhibited morphological alterations and reduced cell–cell adhesion, with AQP5 additionally affecting cell stiffness and membrane fluidity." (PMID 39941100, 2025). "AQP3 and AQP5 were shown to mediate H2O2 transport in pancreatic ductal adenocarcinoma BxPC3 cells." (PMID 39125952, 2024). "In a previous study, AQP3 and AQP5 expression was investigated in pancreatic ductal adenocarcinoma (PDA) human biopsies by immunohistochemistry and, although both AQPs have peroxiporin activity, their expression pattern was different during the development of the tumor." (PMID 35455986, 2022).
cervical carcinoma (4 papers, 2014 to 2024). A carcinoma arising from either the exocervical squamous epithelium or the endocervical glandular epithelium. "Our results indicate that AQP1 and AQP3 are closely associated with tumor vascularization, the progression, invasion and metastasis of cervical carcinoma." (PMID 24918928, 2014). "To uncover the molecular mechanism underlying the oncogenic effects of AQP3 in cervical cancer cells, we found by immunoprecipitation experiments that AQP3 inter-acts with NOX4 and may co-form complexes at the cell membrane." (PMID 38230207, 2024). "To investigate AQP3's role in cervical cancer, we employed lentiviral shRNA to knock down AQP3 in HeLa cells." (PMID 38230207, 2024). "In vivo assays confirmed that the excessive H2O2 transport through AQP3 enhanced the infiltration and metastasis of cervical cancer." (PMID 38230207, 2024). "In conclusion, these findings strongly link AQP3 to the metastatic and invasive traits of cervical cancer cells." (PMID 38230207, 2024). "It is suggested that knockdown of AQP3 inhibits the activation of PI3K/Akt signaling pathway in cervical cancer HeLa cells, and this effect can be partially reversed by PI3K agonists." (PMID 38230207, 2024). "In this preliminary study, we found that the expression of AQP3 in HeLa cell line was highest among the 4 cell lines representing the main molecular subtypes of cervical cancer." (PMID 38230207, 2024). "Taken together, our results suggest that AQP3 promotes cervical cancer invasion and metastasis by regulating NOX4-derived H2O2 transport into cancer cells, thereby activating the Syk/PI3K/Akt signaling pathway." (PMID 38230207, 2024). "AQP1 was localized in the tumor vessels, while AQP3 showed increased expression in cervical cancer, compared to intraepithelial neoplasia, and normal cells." (PMID 33271827, 2020). "Further, AQP3 was also reported to be expressed in the endometrium of women, and AQP3 was also highly abundant in human cervical cancer, but this will be presented in a more detailed fashion in the section related to female disorders." (PMID 33271827, 2020). "AQP3 was localized to the membrane and cytoplasm of normal squamous epithelium and carcinoma cells, showed intense staining in cervical cancer." (PMID 24918928, 2014). "One-way ANOVA, the Χ2 test and rank correlation analysis demonstrated that positive expression rates of AQP1 and AQP3 were significantly related to clinical stage, tumor diameter, lymphatic metastasis and the tumor infiltration depth in cervical carcinoma." (PMID 24918928, 2014). "We observed that AQP1 and AQP3 exhibited different expression patterns in cervical carcinoma, CIN and normal tissues at both the mRNA and protein levels." (PMID 24918928, 2014). "Expression of AQP1 and AQP3 were remarkably upregulated in cervical carcinoma tissues compared to CIN and mild cervicitis." (PMID 24918928, 2014). "The differences in AQP1 and AQP3 mRNA expression between mild cervicitis, early stage and advanced stage cervical carcinoma were significant (P<0.05)." (PMID 24918928, 2014). "Immunofluorescent and immunohistochemical assays were performed to determine the localization and expression of AQP1 and AQP3 in cervicitis, early stage and advanced stage cervical carcinoma." (PMID 24918928, 2014). "In our previous study, we observed that AQP1and AQP3 are the only members of the AQPs family to be overexpressed in cervical cancer." (PMID 24918928, 2014). "We also analyzed the correlation between AQP1 and AQP3 expression and prognosis in cervical carcinoma." (PMID 24918928, 2014). "In summary, AQP1and AQP3 are upregulated in cervical carcinoma in women of Uygur ethnicity from Xinjiang, China." (PMID 24918928, 2014). "We next studied the impact of AQP3 on the invasion capability of cervical cancer cells." (PMID 38230207, 2024).
cervical carcinoma (continued). "In this study, we utilized cervical cancer HeLa cell line and established a xenograft tumor model in nude mice, and then we investigated the role and mechanism of AQP3 in the invasion and metastasis of cervical cancer by controlling NOX4-derived H2O2 signaling." (PMID 38230207, 2024). "Inhibition of the H2O2/Syk/PI3K/Akt signaling axis may be a potentially effective way to treat cervical cancer, and AQP3 could be a potentially effective target for the treatment of cervical cancer." (PMID 38230207, 2024). "The knockdown of AQP3 showed a protective effect against cervical cancer progression." (PMID 38230207, 2024). "Currently, the mechanism by which AQP3 regulates H2O2 transport to promote cervical cancer's malignant progression remains unknown and requires further investigation." (PMID 38230207, 2024). "AQP1 and AQP3 were expressed in mild cervicitis, early stage and advanced stage cervical carcinoma." (PMID 24918928, 2014). "Tumor infiltration depth, treatment protocol, HPV infection status, serum SCC-Ag level, and AQP1 and AQP3 expression were not independent risk factors in cervical carcinoma." (PMID 24918928, 2014). "Upregulation of AQP1 and AQP3 may facilitate progression, invasion and metastasis in cervical carcinoma, suggesting that AQPs may represent potential targets for the treatment of cervical carcinoma in the future." (PMID 24918928, 2014). "AQP1 and AQP3 mRNA expression increased from mild cervicitis to cervical carcinoma." (PMID 24918928, 2014). "In this study, we investigated the different expression of AQP1andAQP3 in both transcription and translation level in the cervical lesions of women of Uygur ethnicity from Xinjiang, China, and analyzed the prognostic value of AQP1 and AQP3 in cervical carcinoma." (PMID 24918928, 2014). "Thus, they indicated that AQP3 might play an important role in carcinogenesis and tumor progression of cervical carcinomas." (PMID 29472315, 2018). "However, multivariate analysis indicated that overexpression of AQP1and AQP3 were not independent risk factors associated with prognosis in cervical cancer." (PMID 24918928, 2014). "AQP3 interacts with NOX4 in the cell membrane, and a large amount of H2O2 flows into the cell through the open AQP3 channel, which acts as a signaling molecule to activate the Syk/PI3K/Akt pathway, promoting the invasion and metastasis of cervical cancer." (PMID 38230207, 2024). "In this study, cervical cancer HeLa cell line was respectively treated with diphenyleneiodonium (DPI), N-Acetylcysteine (NAC) or lentivirus-shRNA- AQP3." (PMID 38230207, 2024). "Positive expression rate of AQP3 gradually increased from mild cervicitis and CIN2-3 to cervical cancer (P<0.05)." (PMID 24918928, 2014). "The results indicate that NOX4-derived H2O2 transmembrane transport induced by growth factors is regulated by AQP3, and AQP3-dependent H2O2 signaling activates intracellular Syk/PI3K/Akt signaling cascades that promote the invasion and metastasis of cervical cancer." (PMID 38230207, 2024).
colon adenocarcinoma (4 papers, 2012 to 2024). "Additionally, a previous study showed that TNF-α promoted a downregulation of AQP3 expression in human colonic adenocarcinoma (HT-29) cells through inhibition of constitutive transcriptional activity of the AQP3 promoter." (PMID 34267676, 2021). "In human colon adenocarcinoma HCT8 cells, treatment with DDAVP, a stable analog of the hormone vasopressin, was previously shown to significantly reduce membrane expression of AQP3, resulting in decreased cell viability." (PMID 39857360, 2024).
dermatitis (4 papers, 2020 to 2024). An inflammatory process affecting the skin. "The deletion of AQP3 effectively inhibited the development of rosacea‐like skin inflammation in LL37‐induced murine models, suggesting its pivotal role in disease pathogenesis." (PMID 39692542, 2024). "Altogether, these data suggest that AQP3 expressed in keratinocytes plays a pivotal role in skin inflammation by regulating NF-κB activation in rosacea." (PMID 37928265, 2023). "Specifically, AQP3 deletion blocked the development of rosacea-like skin inflammation in model mice with LL37-induced rosacea-like disease." (PMID 37928265, 2023). "Our results showed that WT mice exhibited typical rosacea-like dermatitis, including telangiectasia and erythema, whereas Aqp3-/- mice did not develop obvious rosacea-like features." (PMID 37928265, 2023). "The protective effects of PF and PW on UVB-induced skin inflammation and skin barrier damage in human immortalised epidermal keratinocytes (HaCaT) cells (including cell viability, ROS, HO-1, NQO1, IL-1β, IL-8, TNF-α, KLK-7, FLG, AQP3 and Caspase 14 levels) are investigated." (PMID 36771204, 2023).
irritable bowel syndrome (4 papers, 2020 to 2025). Irritable bowel syndrome (IBS) is a chronic functional condition of the lower gastrointestinal (GI) tract characterized by abdominal pain or discomfort and disordered bowel habit (diarrhea, constipation, or fluctuation between the two). "Another study also found that the AQP3 mRNA expression was reduced in the colon of rats with irritable bowel syndrome via NF-κB pathway, which might be associated with liquid water metabolic abnormalities and intestinal permeability alterations." (PMID 38089478, 2023). "It has been reported that the downregulation of AQP3 can regulate liquid water metabolism and intestinal permeability in irritable bowel syndrome (IBS) rats' colon via NF-κB pathway." (PMID 32774435, 2020). "It has been reported that the AQP3 regulates liquid water metabolic abnormalities and intestine permeability alteration in irritable bowel syndrome (IBS) rats via NF-κB pathway." (PMID 32774435, 2020). "For example, Camilleri et al78 found reduced AQP3 mRNA and protein abundance in reconstituted rectal bacteria, predominantly with irritable bowel syndrome, regardless of the presence or absence of bile acid malabsorption, compared with a healthy control group." (PMID 39128069, 2023).
non-small cell lung carcinoma (4 papers, 2012 to 2025). A group of at least three distinct histological types of lung cancer, including non-small cell squamous cell carcinoma, adenocarcinoma, and large cell carcinoma. "In addition, AQP3 expression is suppressed by miR-874, which directly binds to the 3′-untranslated regions of AQP3 mRNA, thereby inhibiting migration and proliferation of non-small-cell lung cancer, indicating multiple levels of AQP3 regulation." (PMID 37175840, 2023).
rosacea (4 papers, 2023 to 2025). A chronic erythematous skin disorder that affects the face. "Based on this evidence, we hypothesized that AQP3 may be implicated in the inflammation characteristic of rosacea." (PMID 37928265, 2023). "For instance, aquaporin 3 (AQP3) overexpression in rosacea activates NF-κB signaling in keratinocytes, promoting chemokine production and inflammatory amplification." (PMID 40474977, 2025). "Tang and colleagues showed that a TXA‐loaded ZIF‐8 presented a higher penetration capacity, based on the activation of the aquaporin‐3 protein (AQP‐3), and a significant improvement of the clinical signs of rosacea and melasma." (PMID 39600220, 2025). "To clarify the functional role of AQP3 in the development of rosacea, we established Aqp3-knockout (Aqp3-/-) mice." (PMID 37928265, 2023). "Through immunofluorescence assays, we found that the expression of AQP3 in CD4+ T cells was enhanced in rosacea patients." (PMID 37928265, 2023). "In a mouse with rosacea induced by LL37 application, AQP3 knockout led to profound resistance to rosacea pathogenesis." (PMID 37928265, 2023). "Performing immunohistochemistry (IHC), we further demonstrated that all samples from rosacea patients exhibited highly intense AQP3 staining in the epidermis and in some of the cells infiltrating the dermis, while HS showed relatively weak AQP3 activity." (PMID 37928265, 2023). "Here, we show that AQP3 expression is increased in epidermal skin lesions from both rosacea patients and model mice." (PMID 37928265, 2023). "To further investigate the molecular mechanisms by which AQP3 is involved in rosacea pathogenesis, we performed RNA sequencing with skin lesions obtained from WT and Aqp3-/- mice at baseline and after LL37 treatment." (PMID 37928265, 2023). "Collectively, these findings suggest that AQP3 is needed for the activation of epidermal NF-κB and chemokine signaling and reveal a previously unrecognized role for AQP3 in Th17 cell-mediated immunity in rosacea pathogenesis." (PMID 37928265, 2023). "In the present study, our results reveal that epidermal AQP3 plays a proinflammatory role in rosacea pathogenesis by activating NF-κB signaling and cells to release chemokines, which recruit CD4+ T cells to lesions in the skin." (PMID 37928265, 2023). "To further explore the possibility that AQP3 is a therapeutic target and exclude the systemic effects of AQP3 global knockout, we investigated whether silencing AQP3 in mice using small interfering RNA (siRNA) protects mice against rosacea." (PMID 37928265, 2023). "Moreover, an RT‒qPCR analysis showed that the expression of rosacea-related signature genes was also decreased in the Aqp3-/- mice compared with the WT mice." (PMID 37928265, 2023). "Taken together, these data suggest that the upregulated expression of AQP3 may be functionally involved in the inflammatory response of rosacea." (PMID 37928265, 2023). "In addition, an RT‒qPCR analysis confirmed our results, suggesting that AQP3 preferentially regulates Th17 cell-polarization-induced inflammation in the context of rosacea." (PMID 37928265, 2023). "To determine whether the increase in AQP3 expression contributes to the activation and differentiation of T cells in rosacea, we examined AQP3 expression in different Th cell subtypes." (PMID 37928265, 2023). "To examine the expression and distribution of AQP3 in rosacea, we first measured the mRNA levels of AQP3 and showed that AQP3 expression was significantly increased in the skin lesion samples from rosacea patients compared to skin samples from healthy individuals (HS)." (PMID 37928265, 2023). "Given that LL37 upregulated AQP3 in the epidermis of rosacea model mice model, we wondered whether it induces AQP3 in keratinocytes in vitro." (PMID 37928265, 2023).
rosacea (continued). "External stimuli, including heat, spicy food, and sun exposure, can trigger and aggravate rosacea 3, 31; therefore, we wondered whether these stimuli can lead to upregulated AQP3 protein expression in keratinocytes." (PMID 37928265, 2023). "Therefore, we speculated that AQP3 may mediate NF-κB activation by transporting H2O2 in cells in the context of rosacea." (PMID 37928265, 2023). "AQP3 may be envisaged as, to our knowledge, a previously unreported therapeutic target for rosacea." (PMID 37928265, 2023). "Hence, we wondered whether the elevated expression of AQP3 in CD4+ T cells is important to rosacea pathogenesis." (PMID 37928265, 2023). "Our previous study revealed that AQP3 is highly expressed in the epidermis and CD4+ T cells of patients with rosacea and experimental mice." (PMID 39692542, 2024). "Hence, we hypothesized that AQP3 may regulate the expression of chemokines in rosacea." (PMID 37928265, 2023). "In summary, AQP3 functions as a proinflammatory regulator in keratinocytes and CD4+ T cells of rosacea skin." (PMID 37928265, 2023). "Our findings reveal that AQP3-mediated activation of NF-κB in keratinocytes and activation of STAT3 in CD4+ T cells acted synergistically and contributed to the inflammation in rosacea." (PMID 37928265, 2023). "The present study demonstrates that AQP3 is upregulated in the epidermal keratinocytes and dermal CD4+ T cells of rosacea patients and model mice." (PMID 37928265, 2023). "Here, we report that aquaporin 3 (AQP3), a channel protein that mediates the transport of water/glycerol, was highly expressed in the epidermis and CD4+ T cells of both rosacea patients and experimental mice." (PMID 37928265, 2023). "Moreover, we show a positive correlation between AQP3 and IGA score, which are used mainly to evaluate the severity of inflammation in rosacea patients." (PMID 37928265, 2023). "Collectively, these data suggest that AQP3 plays an important role in regulating Th17 cell differentiation, which may be mediated by STAT3 activation in the context of rosacea." (PMID 37928265, 2023). "Moreover, to determine the AQP3-mediated synergistic effect between keratinocytes and CD4+ T cells in the pathogenesis of rosacea, we perform the t-cell chemotaxis experiment." (PMID 37928265, 2023). "Furthermore, we isolated CD4+ T cells obtained from dermal cell suspensions obtained from LL37-induced rosacea-like skin samples and verified that AQP3 was elevated in CD4+ dermal T cells but not in CD4- dermal T cells." (PMID 37928265, 2023).
Allergy (3 papers, 2020 to 2024). An allergy is an immune response or reaction to substances that are usually not harmful. "Notably, human AQP3 exhibited maximum values of identity and similarity of 95.5% and 98.6%, respectively, with aquaporin allergy sources." (PMID 39310813, 2024).
basal cell carcinoma (3 papers, 2014 to 2022). A carcinoma involving the basal cells. "The aquaglyceroporin aquaporin-3, AQP3 (AQP3, GeneID: 360), which also transports glycerin in addition to water, is expressed in normal epidermis and overexpressed in basal cell carcinoma and human skin squamous cell carcinomas." (PMID 24653705, 2014). "The absent expression of AQP3 in basal cell carcinoma and sebaceous carcinoma also has some diagnostic value." (PMID 34745849, 2021). "No expression of AQP3 in basal cell carcinoma further confirms the hair follicle origin of basal cell carcinoma." (PMID 34745849, 2021). "Since both basal cell carcinoma and sebaceous carcinoma show negative AQP3 staining, AQP3 is not useful to distinguish basal cell carcinoma with sebaceous differentiation from sebaceous carcinoma." (PMID 34745849, 2021). "No expression of AQP3 in basal cell carcinoma and sebaceous carcinoma might help to elucidate their histogenesis and/or pathogenesis." (PMID 34745849, 2021).